ENSG00000285542 (novel protein, PPM1B-SLC3A1 readthrough)
Gene: Protein-coding gene on chromosome 2 (44,168,851 to 44,320,310, forward strand). Ensembl gene ENSG00000285542.
Genetic constraint (gnomAD): Missense variants: 432 observed, 454.92 expected, observed/expected ratio (o/e) 0.95, 90% interval 0.88 to 1.03. Synonymous variants: 164 observed, 157.56 expected, observed/expected ratio (o/e) 1.04, 90% interval 0.92 to 1.18.